EGFR (epidermal growth factor receptor)
Diseases named in the same sentence as EGFR in open-access papers (continued):
Sharing a sentence is not in itself a finding about the gene and the disease.
tumor (continued). "Toll-like receptor 4/9-cyclooxygenase-2 (COX2) signaling and interleukin (IL)-1β/epidermal growth factor receptor (EGFR)/extracellular signal-regulated kinase (ERK) signaling in tumor cells can be activated by NETs." (PMID 37958984, 2023). "Elevated EGFR expression in tumor cells enhances cell adhesion to the extracellular matrix and facilitates distant metastasis." (PMID 38002335, 2023). "Dysregulation of the Ras-Raf-Mek-ERK, PI3K-Akt-mTOR, PLC- γ 1, signal transducer and activator of transcription, and Src pathways downstream of EGFR are involved in tumor cell proliferation and apoptosis, which are tightly associated with sorafenib resistance." (PMID 36891274, 2023). "As Cabanero and Tsao (2018) suggest, in patients diagnosed with NSCLC, ctDNA analysis can provide tumor resistance responses acquired in real-time to TKIs for EGFR." (PMID 36768828, 2023). "On the other hand, left-sided tumours should be treated with a doublet with an anti-EGFR in the first-line setting." (PMID 37377686, 2023). "Due to its association to different signaling pathways, as the EGFR induced NF-κB activation, MALT1 has been described as an essential protein for tumor progression in preclinical models." (PMID 36745330, 2023). "Collectively, these results indicate that different oncogenes in the EGFR/KRAS/BRAF axis have dramatically different effects on tumor initiation and growth." (PMID 37828026, 2023). "The siRNA and EGFR short peptide vaccine had a high biocompatibility, showed effective tumor immunotherapy, and had an effective role in the downregulation of the expression of PD-L1 in cells compared to the blank group and the PD-L1-siRNA group." (PMID 37754880, 2023). "Collectively, HCD3514 is a highly selective and potent EGFR inhibitor against EGFRC797S triple mutations as well as EGFRT790M double mutations and is confirmed potently anti-tumor activity in preclinical models." (PMID 36605493, 2023). "Bi-specific antibodies designed to bind 4-1BB and a tumor antigen simultaneously, such as Her2, EGFR, or CEACAM5, should result in the selective activation of 4-1BB pathways in the TME." (PMID 37662949, 2023). "The L858R point mutation of exon 21 can improve A-loop stability and enhance tumor cells’ sensitivity to EGFR-TKIs." (PMID 37390230, 2023). "In our study, CXCL9 exhibited higher expression in EGFR–TKI-sensitive samples, consistent with its role in inhibiting tumor-associated angiogenesis and contributing to EGFR–TKI resistance." (PMID 37816585, 2023). "Chromogenic in situ hybridization for EGFR showed spindle cells harboring EGFR amplification in both the low- and high-grade areas of this tumor." (PMID 37650999, 2023). "The assessment of EGFR expression in tumor tissues has been conducted by examining gene amplification, mutation, increased mRNA transcripts, or raised protein levels." (PMID 37895912, 2023). "Herein, we also explored if SPINK1 would act through EGFR to promote tumor-initiating and chemoresistance properties in HCC." (PMID 38030644, 2023). "The anti-tumor efficacy of the “winning” combination of EGFR (erlotinib) and MTOR (MLN0128) inhibitors was further mechanistically investigated in culture and in vivo." (PMID 36831214, 2023). "Of note, how the interactions between tumor cells and immune system affect the response to EGFR-TKI therapy is not completely understood, which limits the development of an effective combination therapy." (PMID 36817465, 2023). "Overall, these results suggested that not only are LAMC2 and EGFR positively correlated in protein expression levels, knocking down either of the two can directly hinder the tumor-promoting activity and function of the other." (PMID 37542131, 2023). "EGFRvIII, a variant of the epidermal growth factor receptor (EGFR), is expressed only in tumors and represents a tumor antigen that can be targeted by CAR-T in GBM." (PMID 37503321, 2023).
tumor (continued). "Third-generation CAR-T cells with an anti-EGFR antibody scFv region inhibited TNBC tumor growth by increasing cytokine secretion and cytolytic activity in mouse allograft models." (PMID 37457288, 2023). "Unfortunately, acquired resistance still occurs in patients after receiving EGFR‐TKIs, leading to tumor recurrence and metastasis." (PMID 36594109, 2023). "The degree of PAI-1 expression was significantly higher in the tumor after acquired resistance to EGFR-TKI than during pretreatment (PAI-1-positive areas of 2.5% vs. 24.1%, respectively, p < 0.05)." (PMID 36831438, 2023). "Among EGFR ex20ins patients, 21/84 (25%) had tumours with PD-L1 greater or equal to 50%, 25/84 (30%) had 1–49% PD-L1, and 30/84 (36%) had PD-L1 < 1%." (PMID 37622996, 2023). "By inhibiting EGFR tyrosine phosphorylation, gefitinib affects downstream signaling cascades in the tumor cell." (PMID 38201251, 2023). "The use of P3-FAX resulted in the depletion of α2,3-linked sialylation on the cell surface, leaving the antibody opsonization of the tumor antigens Her2/neu and EGFR unaltered." (PMID 38138970, 2023). "The competitive specific binding ofcetuximab to EGFR was found to be effective in inhibiting receptorphosphorylation, which in turn impedes the EGFR signaling pathway and resultsin tumor cell proliferation." (PMID 37538799, 2023). "One previous study also reported that EGFR-mutated NSCLC carcinomas were free of T cell infiltration and had decreased proportions of PD-L1+/CD8+ tumor-infiltrating T cells." (PMID 37033978, 2023). "Here, we demonstrate that Cet-ZA ADC can react with CRC-TAF expressing EGFR, making them able to stimulate Vδ2 T lymphocytes with effector phenotype and anti-tumor function." (PMID 36765569, 2023). "In GBC, dasatinib reduced tumor growth in vivo and enhanced the therapeutic response to anti-EGFR treatment." (PMID 37108401, 2023). "Taken together, these data show that the concomitant silencing of EREG and EGFR targeting would be more effective in inhibiting tumor growth and survival." (PMID 36899869, 2023). "The nuclear accumulation of EGFR represents an ideal target for therapeutic intervention as it appears to rarely occur outside the context of cancer, yet drives tumor progression, therapeutic resistance, and correlates with worse patient outcomes." (PMID 37720348, 2023). "For each patient’s primary or recurrent tumour, EGFR amplification status was determined by fluorescence in-situ hybridisation (FISH)." (PMID 36765632, 2023). "In conjunction with this evidence, EGFR-mediated constitutive activation of STAT3 leads to tumor advancement and apoptotic dysregulation in squamous cell carcinoma." (PMID 38170015, 2023). "Formalin-fixed paraffin-embedded (FFPE) tumor blocks from EGFR mutant NSCLC tumors obtained prior to initiation of treatment or after tumor progression during treatment were stained with anti-PDK1 antibody for IHC analysis." (PMID 37169941, 2023). "Estimated personalized PFS curves describe the probability of tumor progression after EGFR-TKI treatment." (PMID 36670497, 2023). "Such a mechanism ensures the maintenance of the EGFR/CDK2 signaling axis, which promotes tumor cell proliferation and provides IDH-wt GBM tumor cells with an additional layer of resistance against targeted EGFR/CDK2 inhibition." (PMID 37936247, 2023). "Our results confirm the benefit of third-line anti-EGFR treatment in L-sided tumors, supporting the predictive role of primary tumor location also in pretreated mCRC patients." (PMID 36895480, 2023). "The EGFR signaling system is well characterized in immortalized cell lines such as HeLa derived from tumor tissues, but much less is known about EGFR function in untransformed multipotent stromal/stem cells (MSCs)." (PMID 37686213, 2023). "All these signals were compared between the LUAD PDX - tumor or cells sensitive to EGFR-TKIs and those resistant to EGFR-TKIs." (PMID 37268635, 2023).
tumor (continued). "In normal ovary, in postmenopausal women, ACE activity was found significantly higher and in an OC xenograft model the inhibition the Angiotensin II, a RAS component, blocked the formation of the tumor spheroids and metastastases in EGFR-dependent manner." (PMID 37041632, 2023). "Detailed mechanistic studies showed that the EGFR mAb cetuximab facilitated dendritic cell priming to augment anti-tumor immunity." (PMID 37631380, 2023). "Previous studies have shown the potential of STAT3 inhibitors in combination with EGFR-TKIs for anti-tumor therapy." (PMID 37649478, 2023). "The idea was that it was possible to stop EGFR-overexpressing tumor proliferation through interference with the EGFR signaling." (PMID 38201251, 2023). "‐Blockage of spheroid formation by clodronate‐liposome‐mediated macrophage depletion or anti‐ICAM‐1 antibodies delayed tumor growth.‐Pharmacological blockade of EGFR delayed tumor growth." (PMID 36658699, 2023). "In PAAD, therapeutic actions against EGFR either with kinase inhibitors or with antibodies have shown disappointing results, and it is known that this tumor harbors an immune-suppressive environment." (PMID 37370859, 2023). "MDSCs and TAMs suppress the anti-tumor cellular responses, promoting an epidermal growth factor receptor (EGFR)/mitogen-activated protein kinase (MAPK)-driven upregulation of programmed death-ligand 1 (PDL1)." (PMID 36769332, 2023). "EGFR can also activate the MAPK signalling cascade, which in turn stimulates transcription factors that drive the expression of genes associated with tumor invasion and metastasis." (PMID 36818231, 2023). "In the meantime, a significant decrease of epidermal growth factor receptor activity and hexokinase-2 expression were seen in kaempferol-treated tumor tissue." (PMID 37239974, 2023). "Patients with a KRAS mutation had more tumor regression in surgical specimens following ChRT and longer DFS following surgery than patients with an EGFR mutation, yet, trended towards a shorter duration of OS." (PMID 37751214, 2023). "A patient-derived EGFR-mutant xenograft model verified that early PI3K/AKT pathway inhibition delays tumor growth in SCLC or NSCLC undergoing transformation." (PMID 36717865, 2023). "Conversely, the number of EGFR-driven tumors was greatly impacted by coincident tumor suppressor inactivation." (PMID 37828026, 2023). "Data were also provided to support the use of anti-EGFR antibodies for tumor detection using PET-based imaging." (PMID 37193364, 2023). "This in vivo phenomenon was linearly correlated with ex vivo tumor EGFR immunohistochemistry and shown to noninvasively detect fewer than 200 tumor cells in draining lymph nodes." (PMID 34651290, 2023). "Our findings confirmed that PD1 blocking and CCR6 can enhance the anti-tumor function of EGFR CAR-T cells in an NSCLC xenograft model, providing an effective treatment strategy to improve the efficacy of CAR-T in NSCLC." (PMID 36982500, 2023). "In particular, TargomiR employs the EGFR-targeting EDV system to precisely deliver miR-16 mimics into EGFR-overexpressing tumor cells in patients with recurrent MPM or NSCLC." (PMID 37430087, 2023). "The efficacy of EGFR inhibition is likely to at least in part be driven by the reshaping of the tumour immune microenvironment, with higher infiltration and proliferation of anti-tumour T cells observed in mouse models following EGFR inhibition." (PMID 37457379, 2023). "Activation of EGFR pathways in NSCLC was associated with decrease in CD8+ TILs, but an increase in tumor-infiltrating FOXP3+ Tregs." (PMID 37340370, 2023). "To note, in one condition (namely EGFR mutant with placebo), the simulation tended to provide a tumor volume that was slightly lower than the observed one, while remaining in the experimental uncertainty that was huge in this particular setting." (PMID 37524705, 2023). "More recently, EGFR-TKIs have shown promise in those NSCLC patients where the tumor has developed brain metastases." (PMID 37190312, 2023).
tumor (continued). "EGFR, a receptor-type tyrosine kinase, is overexpressed and/or mutated in LUAD and controls tumor growth through signaling regulation." (PMID 37065830, 2023). "Further, to optimize the mAb used for ADC technology, a modified tumor specific mAb, named probody has been used that showed enhanced therapeutic index in an EGFR-overexpressing mouse model." (PMID 37671162, 2023). "Taken together, midazolam exhibited anti-tumor effects hallmarked by EGFR pathway inhibition, providing a novel insight into the treatment of NSCLC." (PMID 37305523, 2023). "In this case, tumor primary resection after three years of the initial diagnosis represents a paradigm shift in the treatment of EGFR mutant patients." (PMID 38213544, 2023). "EGFR promotes tumor cell proliferation, differentiation, growth, and distant metastasis by activating downstream signaling pathways, such as PI3K and MAPK." (PMID 37614311, 2023). "Although afatinib is one of the standard treatments for patients with EGFR-mutated NSCLC, it is necessary to develop a combination therapy to overcome poor treatment outcomes, such as drug resistance and tumor recurrence." (PMID 37298389, 2023). "The EGFR/MEK/ERK pathway has been reported to be involved in tumor progression in a variety of cancers." (PMID 36653376, 2023). "In this study, we investigate the anti-GBM tumor effects of the EGFR inhibitor SMUZ106 in both in vitro and in vivo conditions." (PMID 37242743, 2023). "Regarding the suggested interplay between the two axes CD47:SIRPα and HLA class I:LILRB1 in counteracting effective ADCP of tumor cells as demonstrated for anti-EpCAM or anti-EGFR antibodies, additional antibody combinations were studied." (PMID 37781391, 2023). "Subsequently, in order to exclude the effect of tumor interstitial, we used multiplex immunohistochemistry to examine immune cell infiltration in the tumor parenchyma of EGFR-mutant LUAD, removing the influence of the tumor mesenchyme on the process." (PMID 36756152, 2023). "Intratumoral heterogeneity is an important cause of treatment failure and refers to the presence of heterogeneous targeted molecules (such as EGFR) in tumor tissues; that is, EGFR-mutant and WT clones in the same tumor." (PMID 37754531, 2023). "EGFR mediates resistance of tumour to radiation through activating downstream oncogenic pathways involved in tumour progression." (PMID 37177859, 2023). "The fluorescence reaction of EGFR (red fluorescence) and Src (green fluorescence) in tumor tissues was decreased qualitatively following sustained calcium supply." (PMID 37686097, 2023). "HER2 plays a critical role in driving tumor formation and progression, by forming homodimers and heterodimers with members of its receptor tyrosine kinase family including HER1/EGFR and HER3." (PMID 37662839, 2023). "EGFR-TKIs can induce protective autophagy in various tumor cells, such as LUAD, leading to drug resistance." (PMID 37596251, 2023). "Cetuximab is a monoclonal antibody that binds epidermal growth factor receptor (EGFR) on tumour cells." (PMID 38130720, 2023). "Immunohistochemical analysis comparing the EGFR expression between trametinib‐treated and vehicle‐treated PDXs showed that trametinib treatment induced EGFR expression in most tumor cells." (PMID 37501404, 2023). "A mouse in vitro study demonstrated that the production of VGF can cause the epithelial-mesenchymal transition (EMT), the dispersion of tumor cells, and resistance to EGFR inhibitors." (PMID 37624511, 2023).
tumor (continued). "Analysis of region 3 investigating cycling (K) and noncycling (T) tumor cells revealed immense cellular heterogeneity, especially in the progenitor tumor cell phenotype and EGFR, NF1, and PDGFRA gene expression." (PMID 38077210, 2023). "Dacomitinib (EGFR, ErbB-2, and ErbB4, irreversible inhibitor) was efficient in inhibiting the tumor volume of HNSCC and acted as a radiosensitizing agent in HNSCC." (PMID 36646686, 2023). "The tumor showed EGFR C797S, T790M, exon 19 deletion (T751_I759>N), CDK4 amplification, MDM2 amplification, CDKN2A/B loss, MTAP loss, low MSI, low TMB and negative PD-L1." (PMID 38111812, 2023). "In P13, EGFR KDD was detected both in tumor tissue and plasma after the patient progressed on icotinib." (PMID 36325957, 2023). "This drug also restores MHC-I expression in tumor cells, hindering one of the EGFR immune-escape ways." (PMID 37189730, 2023). "Cetuximab-IR700 antibody-dye conjugate specifically binds EGFR on tumor cells and induces rapid cell death upon administration of applied light." (PMID 35776159, 2023). "Gefitinib, one of the epidermal growth factor receptor (EGFR)-tyrosine kinase inhibitors, inhibited the phosphorylation of EGFR in epithelial OC tumor cells." (PMID 36742380, 2023). "Several oncogenic signaling pathways, including Src/STAT3, EGFR, HER2, MAPK, AKT/mTOR, WNT/-catenin and miRNA-related pathways, have been associated with changes in tumor cell surface CD24 expression." (PMID 37846296, 2023). "As in other tumours, KRAS mutations correlate with worse outcome due to the acquired resistance to epidermal growth factor receptor (EGFR) inhibitors." (PMID 37942486, 2023). "Abbas demonstrated an increase in mEGFR expression with an increasing histologic grade of the tumor in 30 OSCC and concluded that EGFR can be used as an indicator of tumor aggressiveness." (PMID 36982894, 2023). "First, as the EGFR pathway is vulnerable to tumor evolution, timely sampling is mandatory to target EGFR axis." (PMID 37537946, 2023). "In conclusion, our results demonstrated a different benefit from third-line anti-EGFR therapy according to primary tumor site, confirming the role of L-sided tumor in predicting benefit from third-line anti-EGFR vs R/T." (PMID 36895480, 2023). "The pathways involved in treatment have yet to be elucidated, making the role of EGFR in GBM unclear concerning both the survival of tumor cells and the potential for thromboembolic complications." (PMID 37232831, 2023). "NOX1 activation, increased oxidant production and EGFR activation can lead to the upregulation of MMPs which can then promote tumor metastasis." (PMID 37516013, 2023). "Thirteen cases were histologically reviewed, characterized for tumor‐infiltrating lymphocytes (TILs), and were subjected to immunohistochemistry for programmed death‐ligand 1 (PD‐L1, clone 22C3), EGFR, and amphiregulin (AREG)." (PMID 36916425, 2023). "Characterization of a panel of NKCEs revealed dose‐dependent triggering of NK cell mediated lysis of EGFR‐overexpressing tumor cells with potencies in the picomolar range." (PMID 36775946, 2023). "Aberrant activation of SRC and EGFR is observed in most human malignancies, suggesting functional cooperativity to promote tumor development." (PMID 37120696, 2023). "In PN21 (a pancreatic tumour), ON33 (a serous ovarian tumour), and BN16 (a TNBC tumour), EGFR/Notch-targeting bispecific antibodies demonstrated significant efficacy in combination with the PARP inhibitor talazoparib." (PMID 37441599, 2023). "A minority of laboratories used a higher threshold for evaluating EGFR status with a single-test approach (3/50 used ≥30%, 1/50 used ≥50% and 1/50 used ≥70%), while 6.0% (3/50) used a tumour cell threshold of ≥1%." (PMID 37713929, 2023). "We also compared its tumor cell killing effect with erlotinib, which is one of the current drug options for the treatment of NSCLC patients with EGFR exon 19 deletions or exon 21 L858R substitution mutational status." (PMID 37111634, 2023).